CD163 (CD163 molecule)
Diseases named in the same sentence as CD163 in open-access papers (continued):
Sharing a sentence is not in itself a finding about the gene and the disease.
allergic asthma (3 papers, 2020 to 2021). A asthma with a basis in a pathological type I hypersensitivity reaction. "In addition, our observation of an allergic asthma-driven increased expression of MafB in tAMs may be in line with reports that Mafb upregulates the expression of M2 polarization markers such as MRC1 and CD163." (PMID 33050608, 2020).
amyloid (3 papers, 2019 to 2025). "An animal model study reported that increased perivascular macrophage (e.g., CD163) turnover promotes vascular Aβ clearance, suggesting that activating perivascular macrophage could be a potential therapeutic strategy for clearing vascular amyloids." (PMID 40004604, 2025).
aneurysm (3 papers, 2022 to 2024). Bulging or ballooning in an area of an artery secondary to arterial wall weakening. "Flow cytometry revealed anti‐inflammatory M2 (CD45+CD11b+CD163+) macrophages in BBAs are significantly enriched in numbers compared with both M1 (CD45+CD11b+CD86+) and M2 (CD45+CD11b+CD163+) macrophages in saccular aneurysms." (PMID 34970805, 2022). "The immunohistochemical staining was used to analyze the infiltration of pro-inflammatory (CD68) and anti-inflammatory macrophages (CD163), T helper (CD4) and T killer cells (CD8), and B (CD79a) and plasma cells (CD138) in all three layers of aneurysms of both groups." (PMID 34656077, 2022).
apical periodontitis (3 papers, 2022 to 2024). "Notably, the infiltration of the M1 sub-type Mφs (CD86+), M2 sub-type Mφs (CD163+) and M1/M2 ratio in apical periodontitis was significantly higher than that in the Cont group." (PMID 38612664, 2024).
autoimmune thyroid disease (3 papers, 2021 to 2025). Inflammatory disease of the thyroid gland due to autoimmune responses leading to lymphocytic infiltration of the gland. "Furthermore, CD14 + CD163 high monocyte DEGs were enriched in chemokine signaling pathways, antigen processing and presentation, autoimmune thyroid disease." (PMID 37041166, 2023). "Although CD163 is expressed both in the tumor microenvironment and in autoimmune thyroid disease, necrotic cells are not present in autoimmune thyroid disease, pointing to the distinct background of ir thyroiditis." (PMID 34771441, 2021).
B cell lymphomas (3 papers, 2021 to 2022). "CD163 is widely accepted as the surface marker of M2 macrophages, which play an important role in B-cell lymphoma by restraining host antitumor immune effector responses." (PMID 36072582, 2022). "The highest amount of both M1 (iNOS+) and M2 (CD204+ and CD163+) subtypes were observed in B-cell lymphomas." (PMID 34438760, 2021). "Interestingly, in a pre-clinical mouse model of B cell lymphomas, Ly6Clow monocytes (corresponding to the ncMO) accumulated and showed high levels of immunosuppressive genes (PD-L1, PD-L2, Arg1, IDO1, and CD163) associated with suppression of T cell proliferation." (PMID 34975843, 2021).
bladder tumor (3 papers, 2017 to 2024). "The results showed that, consistent with literature reports, CD163 was highly expressed in bladder tumor tissues, while INOS was weakly expressed in microenvironment." (PMID 35603205, 2022).
chordoma (3 papers, 2023 to 2024). Chordomas are rare malignant tumors arising from embryonic remnants of the notochord in axial skeleton. "We found that macrophages were enriched in primary chordomas, and the results were confirmed by IHC with the macrophage markers CD68 and CD163." (PMID 37784253, 2023).
chronic heart failure (3 papers, 2022 to 2025). "Additionally, this information can influence clinical practice, as changes in plasma levels of CD163 have been shown to precede adverse cardiovascular events in patients with chronic heart failure." (PMID 39202593, 2024). "The results of this study show that the lung infections of patients with chronic heart failure in hospital are mainly gram-negative bacteria, and the detection of sTREM-1, s-CD163 and sTWEAK levels is of certain value in judging the condition and prognosis." (PMID 35480505, 2022).
cognitive decline (3 papers, 2019 to 2023). "In consonance with these data, it has been demonstrated the increase in the soluble form of Cd163 in cerebrospinal fluid (CSF) in late Parkinson’s disease (PD) cases that was associated with cognitive decline condition." (PMID 36855152, 2023). "We note, however, that there were no sex differences in the association of CD163 with cognitive decline." (PMID 31555121, 2019).
Cutaneous T cell Lymphoma (3 papers, 2020 to 2025). "Studies have linked CD163(+) M2 macrophages to the progression of cutaneous T cell lymphoma." (PMID 40539722, 2025).
diffuse-type giant cell tumor (3 papers, 2014 to 2017). "Results from a phase I clinical trial demonstrated that the CSF-1R-targeted monoclonal antibody RG7155 depleted CSF-1R+ CD163+ macrophages in tumor tissues and had significant clinical benefit in patients with diffuse-type giant cell tumors." (PMID 28424405, 2017). "The clinical activity of RG7155 was evaluated in patients with diffuse-type giant cell tumor and was shown to induce a striking reduction in the CSF-1R+CD163+ macrophage population within tumor tissues." (PMID 25125485, 2014). "According to Ries (2014), patients with diffuse-type giant cell tumor, the clinical activity of RG7155 was evaluated and was revealed to induce a striking reduction in the CSF-1R + CD163+ macrophage population within tumor tissues." (PMID 29450136, 2017).
diverticulitis (3 papers, 2013 to 2022). An infection that develops in the diverticula of the intestinal tract. "Additionally, recent evidence from the histopathology analysis of colon from patients with complicated diverticulitis found an increase in the amount of activated CD68+ CD163+ macrophages, which also correlated with steroid intake, compared to those with chronic, recurrent diverticulitis." (PMID 32635383, 2020).
Ebola virus disease (3 papers, 2019 to 2024). "In a recent study, macrophage activation maker soluble CD163 has been found upregulated in severe Ebola virus disease." (PMID 39066167, 2024).
epilepsy (3 papers, 2021 to 2024). A brain disorder characterized by episodes of abnormally increased neuronal discharge resulting in transient episodes of sensory or motor neurological dysfunction, or psychic dysfunction. "Although Iba1+ CD14+ or CD163+ cells were identified in epilepsy tissue, where present, they were predominantly associated with blood vessels, indicative of perivascular macrophage expression." (PMID 34286275, 2021). "Colabeling of Iba1 with proposed TAM-specific markers CD14 and CD163 revealed a subset of both Iba1+ CD14+ or CD163+ and Iba1+ CD14− or CD163− cells in both tumor and epilepsy tissue." (PMID 34286275, 2021). "Comparison of the mean single-cell CD14 or CD163 average intensity per case revealed an upregulation of both CD14 and CD163 in gated microglia from tumor tissue when compared to epilepsy tissue, showing microglia have the capacity to upregulate these markers in the context of tumors." (PMID 34286275, 2021). "Similarly, triple labeling with Iba1, P2RY12, and CD163 revealed that while epilepsy tissue is comprised almost entirely of CD163low cells, grade IV tumor tissue contained varying proportions of CD163high to CD163low cells (Figure 4A3 and B3)." (PMID 34286275, 2021).
Erdheim-Chester disease (3 papers, 2023 to 2026). "Erdheim-Chester disease, on the other hand, is positive for CD68 and CD163, may express factor XIIIa, and is negative for langerin and CD1a; S100 may also be expressed." (PMID 40398847, 2025).
glomerular diseases (3 papers, 2021 to 2025). "Contrary to reports in glomerular diseases, usCD163 did not correlate with CD163 staining, either in AIN patients (n = 13) or in ATN patients (n = 5, data not shown)." (PMID 40052170, 2025). "Compared with those in SLE patients without LN, patients with other glomerular diseases, and healthy controls, the levels of urinary soluble CD163 in patients with active LN were shown to be significantly greater, suggesting that urinary soluble CD163 may serve as a biomarker of LN." (PMID 39611168, 2024).
head and neck cancer (3 papers, 2023 to 2024). A primary or metastatic malignant neoplasm affecting the head and neck. "Noticing the high densities of CD163+macrophages in the current study, it is plausible that CD163+macrophages play a central role in resistance to ICI in head and neck cancers." (PMID 39053947, 2024). "As for head and neck cancer, most of the previous research detected M2 macrophage by surface expression of CD68 and CD163." (PMID 36864443, 2023).
hemorrhagic fever (3 papers, 2014 to 2024). An infectious disease caused by certain viruses or bacteria that can damage the walls of tiny blood vessels, making them leak, and can hamper the blood's ability to clot and cause severe, life-threatening illness. "Moreover, elevated levels of secreted CD163 (sCD163) have been associated with both EVD and hantavirus-induced hemorrhagic fever with renal syndrome." (PMID 40295691, 2024).
idiopathic membranous nephropathy (3 papers, 2018 to 2024). "Patients with early stage of idiopathic membranous nephropathy had higher levels of circulating CD14+/CD163+, CD14+/CD163+/CD206+, and CD14+/CD163+/CD206+/CD115+ macrophages in comparison with healthy controls." (PMID 34307414, 2021).
keloid (3 papers, 2019 to 2023). An irregularly shaped, elevated mark on the skin caused by deposits of excessive amounts of collagen during wound healing. "Importantly, keloid implantations revealed uniform pathological characteristics similar to that of patient keloids confirmed by H&E, Masson’s trichrome staining, and CD163 IHC staining." (PMID 36757802, 2023). "Moreover, the CD163+/CD68+ ratio was higher in keloids compared with normal skins (P < 0.05), indicating that enriched macrophages in keloids were mostly the M2 type." (PMID 36757802, 2023). "Furthermore, two modules of macrophages (Module2: highly expresses RNASE1, C1QA, CD163, CD14, C1QC, FCGRT, and MS4A7; Module10: highly expresses APOC1, CTSB, CTSL, and TYROBP), which exhibited the characteristics of TAMs, increased significantly in keloid." (PMID 35990663, 2022).
laryngeal squamous cell carcinoma (3 papers, 2022 to 2023). A squamous cell carcinoma that arises from the larynx. "In the present study, the expression of CD163+ TAMs was analyzed in laryngeal squamous cell carcinomas (LSCCs) using immunohistochemistry, and this expression was correlated with the clinical and pathological characteristics of LSCC patients." (PMID 37082492, 2023). "HMGB1, CD163, and D2-40 in laryngeal squamous cell carcinoma (LSCC, n = 123), laryngeal precursor lesions (LPLs, n = 102), and vocal polyp (VP, n = 55) were analyzed by immunohistochemistry." (PMID 35280439, 2022). "HMGB1+CD163+ M2 macrophages were found as detrimental prognostic factors for OS in laryngeal squamous cell carcinoma patients." (PMID 36686729, 2022).
leukopenia (3 papers, 2013 to 2022). "Taken together, these observations indicate rapid leukopenia after the onset of LPS infusion, which was followed by an increase in the polymorphonuclear cells and expansion of the CD14+CD163+ monocytes, especially in the control animals." (PMID 35566768, 2022).
medulloblastoma (3 papers, 2022 to 2026). A malignant, invasive embryonal neoplasm arising from the cerebellum. "Interestingly, CD163, a marker associated with immunosuppressive myeloid cells, was also elevated in DIPG, ATRT, and medulloblastoma (WNT, SHH) tumors." (PMID 41541220, 2026). "Different proportions of macrophages were found in the collected medulloblastoma tissues, and large amounts of CD68+HLA-DR+CD163+ cells were found." (PMID 40303994, 2025). "We obtained a total of 71 paraffin sections from patients with medulloblastoma, and detected the activated phenotype (M1/M2) by monoclonal antibodies for CD68, HLA-DR and CD163 with multiple fluorescence immunohistochemistry method." (PMID 35860588, 2022).
meningitis (3 papers, 2009 to 2022). A disorder characterized by acute inflammation of the meninges of the brain and/or spinal cord. "In one study, the diagnostic value of serum soluble CD163 was evaluated and compared with that of CRT and PCT for meningitis in an observational cohort consisting of 55 patients suspected of having meningitis." (PMID 35524265, 2022).
Merkel cell carcinoma (3 papers, 2020 to 2022). "Non-melanoma skin cancers such as extramammary Paget’s disease (EMPD), cutaneous squamous cell carcinoma (cSCC) and Merkel cell carcinoma (MCC) also possess heterogeneous CD163+ TAMs that could secrete an array of cytokines and chemokines in lesional skin to regulate the tumor microenvironment." (PMID 32707850, 2020). "Substantial numbers of VEGF-C+ CD68+ CD163+ TAMs were distributed in the lesional skin of Merkel cell carcinoma, and expression of CD200 in tumor cells induces immunosuppressive CD163+ CD200R+ M2 TAMs and Foxp3+ Tregs to maintain the immunosuppressive tumor microenvironment." (PMID 35409404, 2022).
monocytic leukemia (3 papers, 2015 to 2019). "In our study, the TPA‐treated human monocytic leukaemia cell line THP‐1 was used as an efficient model for CD163+ MΦs in TL." (PMID 31890299, 2019). "Conditioned medium was harvested from the CD163+ human monocytic leukaemia cell line, THP‐1." (PMID 31890299, 2019). "The frequencies of CD86+ and CD163+ cells and expression levels of these markers as well as the cytokines IL-12 and IL-10 were measured in THP-1- (human monocytic leukemia cell) derived macrophages." (PMID 30276219, 2018). "Among them, HS and monocytic leukemia have some similarities in their IHC phenotypes, as both can express one or more monocytic neoplasm antigens, such as CD68, CD163 and lysozyme." (PMID 26187047, 2015).
mucinous adenocarcinoma (3 papers, 2019 to 2022). An invasive adenocarcinoma composed of malignant glandular cells which contain intracytoplasmic mucin. "The levels of CD163+ M2 macrophage were low in signet ring cell carcinoma and mucinous adenocarcinoma but ample in poor-differentiated adenocarcinoma." (PMID 31174544, 2019).
mycosis fungoides (3 papers, 2022 to 2026). Classical mycosis fungoides is the most common type of mycosis fungoides (MF), a form of cutaneous T-cell lymphoma, and is characterized by slow progression from patches to more infiltrated plaques and eventually to tumors. "Materials and Methods: This retrospective study evaluated the immunohistochemical expression of CD47, CD163, and B7-H3 in 46 patients with early-stage mycosis fungoides (MF) and 46 patients with large plaque parapsoriasis (LPP)." (PMID 42075550, 2026). "Additionally, for mycosis fungoides (MF) and Sézary syndrome (SS), the high ratio of CD163 to CD68 in the tumor stages of MF and SS indicates M2 polarization of tumor-associated macrophages (TAMs) and correlates with tumor progression." (PMID 40426926, 2025). "For example, the production of IL-4 is increased in the cancer stroma of the advanced stage compared to the early stage in mycosis fungoides, leading to an increased ratio of CD163+CD206+ M2 polarized TAMs, which could be a measure of the transition to the advanced stage." (PMID 35409404, 2022). "Notably, CD163+CD206+ TAMs produce M2 macrophage-related chemokines such as CCL22 by the stimulation of IL-4 in cancer stroma, which leads to recruitment of CCR4+ lymphoma cells to develop tumor formation in mycosis fungoides." (PMID 35409404, 2022).
myeloid leukemia (3 papers, 2013 to 2022). A clonal proliferation of myeloid cells and their precursors in the bone marrow, peripheral blood, and spleen. "In our study, IL-4 could induce the expression of M2 markers including IL-10, TGF-β, and CD163 as well as some chemokines including CCL-17 and CCL-22 in human myeloid leukemia mononuclear THP-1 cells." (PMID 35996149, 2022).
nasal polyp (3 papers, 2011 to 2024). "Immunohistochemical staining of serial sections for FABP1, SMA, CD163, and MBP was performed on 4-μm sections of paraffinized nasal polyp samples." (PMID 21829647, 2011). "The mRNA expression of CD206 and CD163, known as markers of M2 macrophages, as well as the expression of mRNA MMP12, were examined in normal uncinate process (UP), CRS without nasal polyp (CRSsNP) UP, CRS with nasal polyp (CRSwNP) UP, and CRSwNP NP tissues." (PMID 39739687, 2024).
non-Hodgkin lymphoma (3 papers, 2024 to 2025). Distinct from Hodgkin lymphoma both morphologically and biologically, non-Hodgkin lymphoma (NHL) is characterized by the absence of Reed-Sternberg cells, can occur at any age, and usually presents as a localized or generalized lymphadenopathy associated with fever and weight loss. "HS is diagnosed using positive immunohistochemistry for histiocytic markers, such as CD68, CD4, CD163, or lysozyme, and can present in an isolated form or be associated with other hematologic malignancies, such as non-Hodgkin lymphoma (NHL) or acute leukemia." (PMID 40066099, 2025). "In non-Hodgkin lymphoma, while CD68-positive content has been correlated with improved survival, an increased CD163/CD68 ratio predicts worse prognosis." (PMID 41239536, 2025).
oral epithelial dysplasia (3 papers, 2014 to 2024). "Using immunohistochemistry, the expression of CD163 (a protein marker for M2 macrophages) in the oral tissue sections increased gradually from normal oral mucosa to mild, moderate and severe stages of oral epithelial dysplasia (abbreviated as MED, MoED, and SED, respectively) and OSCC." (PMID 39160581, 2024).
oral lichen planus (3 papers, 2024 to 2025). Oral lichen planus is a chronic inflammatory oral condition of unknown aetiology characterized by T-cell-mediated chronic immune response and abnormal epithelial keratinization cycle. "In a cohort including Oral Lichen Planus (OLP) and Oral Lichenoid Lesions (OLL), CD163+ infiltration is highest in dysplastic OLL, followed by dysplastic OLP, non-dysplastic OLP and finally non-dysplastic OLL; paired analysis revealed a significant difference between these groups." (PMID 40432828, 2025). "Additionally, Oral Lichen Planus showed a significantly (p=0.029) increased CD68 and CD163 cell density and Labeling Index." (PMID 40297579, 2025). "Therefore this study aimed to compare the immune expression of β-catenin & CD163 in dysplastic /non-dysplastic cases of Oral lichen planus & oral lichenoid lesion." (PMID 39327577, 2024).
pancreatitis (3 papers, 2021 to 2024). Inflammation of the pancreas. "Clinically, UBE2M expression remarkably decreases in human CP tissues compared with normal specimens and the levels of CCL5 and M2 marker CD163 are negatively correlated with UBE2M intensity, suggesting that neddylation is involved in the pathogenesis of pancreatitis." (PMID 33723230, 2021).
primary biliary cholangitis (3 papers, 2019 to 2023). Primary biliary cholangitis (PBC) is a chronic and slowly progressive cholestatic liver disease of autoimmune etiology characterized by injury of the intrahepatic bile ducts that may eventually lead to liver failure. "The macrophage activation marker soluble (s)CD163 is associated with disease severity and prognosis in patients with primary biliary cholangitis (PBC)." (PMID 36972379, 2023).
pulmonary hypertension (3 papers, 2018 to 2024). Increased pressure within the pulmonary circulation due to lung or heart disorder. "Previous studies in children and adults with SCD have shown increased soluble CD163 levels in the plasma that correlated with pulmonary hypertension and vasoocclusion." (PMID 38682236, 2024).